EPO (erythropoietin)
Diseases named in the same sentence as EPO in open-access papers (continued):
Sharing a sentence is not in itself a finding about the gene and the disease.
polycythemia (207 papers, 2006 to 2026). Abnormally high mass or concentration of red blood cells in the blood, either due to an increase in erythropoiesis or a decrease in plasma volume. "In mice, loss of IRP1 causes polycythemia through translational de-repression of HIF2α mRNA, which increases renal erythropoietin production." (PMID 41493805, 2026). "Older age (p < 0.01), higher platelet count (p < 0.01), and lower EPO (p < 0.01) were associated with JAK2 mutant erythrocytosis in a multivariate analysis." (PMID 40806795, 2025). "It causes polycythemia by increasing the set point of erythropoietin to higher hemoglobin levels and increasing iron bioavailability by decreasing ferritin and hepcidin levels." (PMID 40656289, 2025). "Autonomous EPO production is a reported cause of secondary polycythemia in a variety of malignant tumors, including renal cell carcinoma, meningioma, and hepatocellular carcinoma [6,9,]." (PMID 40502212, 2025). "The transcription factor HIF-2 is a key determinant of manganese excess, erythropoietin excess, and polycythemia in SLC30A10 deficiency, which underlies inherited manganese excess." (PMID 38652538, 2024). "In TOF, we see a right-to-left shunt, which causes the mixing of oxygenated blood with deoxygenated blood, leading to acquired secondary polycythemia [SP] erythropoietin-associated hypoxia." (PMID 39286683, 2024). "Other cases of idiopathic erythrocytosis have proven to be driven by germline mutations of the globin genes or genes involved in the erythropoietin (EPO) or oxygen-sensing signalling pathways." (PMID 39335122, 2024). "To further investigate the basis of EPO excess and polycythemia in SLC30A10 deficiency, we interrogated SLC39A14." (PMID 38652538, 2024). "Investigations for secondary causes of erythrocytosis were unremarkable so a diagnosis of primary erythrocytosis was made; a serum erythropoietin measurement returned normal 3 weeks after presentation supporting this diagnosis." (PMID 39473196, 2024). "Hepatic Hif2a deficiency corrected erythropoietin expression and polycythemia and attenuated aberrant hepatic gene expression in Slc30a10-deficient mice, while hepatic Hif1a deficiency had no discernible impact." (PMID 38652538, 2024). "In conclusion, we present a case of severe hydronephrosis associated with polycythemia and a relatively low EPO level." (PMID 39767963, 2024). "This suggested that SLC39A14-dependent import of Mn into liver drives EPO excess and polycythemia in SLC30A10 deficiency." (PMID 38652538, 2024). "Primary erythrocytosis is secondary to myeloproliferative diseases such as polycythemia vera (PV), while secondary erythrocytosis is associated with elevated serum erythropoietin (EPO) levels." (PMID 39165680, 2024). "Various renal conditions, such as renal transplantation, renal artery stenosis, cysts, and hydronephrosis, can also cause secondary polycythemia by increasing EPO production." (PMID 39767963, 2024). "Nephrotic range proteinuria causes nephrosarca leading to renal hypoxia which causes increased EPO and IL-8 production, this is proposed to cause secondary polycythemia in NS." (PMID 36811053, 2023). "Relative polycythemia is caused by reduced plasma volume, whereas absolute polycythemia usually results from EPO-producing diseases such as hypoxia or tumors." (PMID 36890599, 2023). "The development of polycythemia is associated with the coordination between the upregulation of EPO and induction of HO-1 during chronic hypoxia." (PMID 36977025, 2023). "Unlike previous reports, we measured EPO levels before and after hydronephrosis treatment and linked the EPO production to polycythemia." (PMID 36890599, 2023). "Gestational diabetes is associated with neonatal polycythemia, possibly due to elevated insulin and erythropoietin." (PMID 35232426, 2022).
polycythemia (continued). "Up to 50% of patients with apparent congenital erythrocytosis and elevated serum EPO appear to have a mutation in the VHL gene." (PMID 35205407, 2022). "The pathophysiology of T therapy causing erythrocytosis is suspected to be multifactorial, involving an increased erythropoietin setpoint, decreased hepcidin, and increased estradiol." (PMID 35822152, 2022). "Unlike SLC39A14 deficiency, SLC30A10 deficiency causes erythropoietin excess and polycythemia, although the link between Mn excess and erythropoietin excess has yet to be firmly established." (PMID 34051234, 2021). "In contrast to SLC39A14 deficiency, SLC30A10 deficiency results in polycythemia and excess levels of erythropoietin, a hormone that stimulates RBC synthesis." (PMID 34051234, 2021). "In Irp1–/– mice, elevated Hif2α upregulates erythropoietin (EPO), causing the mice to develop polycythemia and pulmonary hypertension." (PMID 34675764, 2021). "In 2006, a PHD2 mutation (P317R) was implicated in a family with erythrocytosis; EPO levels were inappropriately normal, pointing toward secondary erythrocytosis." (PMID 34021251, 2021). "As erythrocythemia can be secondarily caused by increased EPO levels, we measured the serum EPO levels in Lrfn2 KO mice and found that it was significantly decreased (- 6.7%, P = 0.022)." (PMID 33481887, 2021). "In current classifications of pediatric erythrocytosis, germline mutations resulting in elevated erythropoietin (EPO) levels are classified as secondary erythrocytosis." (PMID 33712866, 2021). "In a pedigree with 10 affected members across four generations with erythrocytosis, a mutation in EPO co-segregated with disease." (PMID 34440325, 2021). "Remarkably, an in silico study identified almost thirty genetic variants of the EPOR and seven variants of the EPO gene associated with erythrocytosis or increased hematocrit in humans." (PMID 33143240, 2020). "Mixed polycythemia, such as Chuvash polycythemia caused by VHLR200W mutation, has features of both primary and secondary polycythemias characterized by elevated EPO and erythroid progenitors hypersensitive to EPO." (PMID 31091718, 2019). "In contrast, truncating mutations removing only parts of the intracellular EPO-R C-terminus that bind negative regulators have been reported to associate with primary erythrocytosis, with low EPO and high haemoglobin levels 14–16, 32–39." (PMID 30271932, 2018). "Inherited erythrocytosis are related to excess erythropoietin (EPO) synthesis or to gain-of-function mutations inEPOR that activate JAK260." (PMID 29399328, 2018). "This is because of the risk for these individuals to develop erythrocytosis secondary to the elevated erythropoietin levels present." (PMID 29696082, 2018). "Mutations in prolyl hydroxylase domain (PHD) 1 and 2 and hypoxia-inducible factor type 2A (HIF2A) genes cause a syndromic presentation with polycythemia and erythropoietin secreting neuroendocrine malignancies." (PMID 29534684, 2018). "In combination with the patient’s recovery from “PV”, we confirmed that his erythrocytosis was caused by chRCC due to EPO production." (PMID 28877745, 2017). "HIF degrading prolylhydroxylase 2 SNPs are known to be associated with erythrocytosis in humans and PHD2 deficiency evokes erythrocytosis by activating the renal erythropoietin pathway in mice." (PMID 28613249, 2017). "The presence of the activating JAK2-V617F mutation in >95% of PV cases likely compensates for the low EPO production by rendering erythroid progenitors highly responsive to low doses of EPO, to result in polycythemia." (PMID 26538820, 2015). "In particular, a multicenter study on a cohort of 116 PV reported a significant reduction in rates of EPO in 85% of patients compared to secondary polycythemia, confirming the interest of the diagnostic assessment of serum EPO in PV." (PMID 26525644, 2015).
polycythemia (continued). "Based on the results of immunohistochemistry, EIA and the clinical course, polycythemia was caused by high EPO production from the resected kidney." (PMID 25295086, 2014). "We report a case of erythrocytosis associated with a large uterine leiomyoma, in which specific immunostaining for erythropoietin was positive." (PMID 24551466, 2014). "As polycythemia diminished following nephrectomy, EPO production from the resected kidney appeared to cause polycythemia." (PMID 25295086, 2014). "Laboratory evaluation revealed erythrocytosis with low serum erythropoietin, and testing for the JAK2V617F mutation was positive, confirming a diagnosis of polycythemia vera." (PMID 25143825, 2014). "In this scenario, we propose a molecular strategy for evaluating genes regarding oxygen sensing and erythropoietin signaling pathways in cases of idiopathic erythrocytosis with suspected congenital causes." (PMID 24363938, 2013). "Mice repeatedly administered the EPO analog darbepoetin develop erythrocytosis and splenomegaly – both major diagnostic criteria for PV - over a period of 7 days." (PMID 22623993, 2012). "Beyond this, when C-terminal truncated hEPOR-T mutant alleles as harbored by polycythemia patients are co-expressed with the wild-type EPOR in EPO-dependent erythroid progenitors, several specific events become altered." (PMID 22253704, 2012). "The method allowed to identify mutant patients which, as previously reported for exon 12 mutated patients, presented with erythrocytosis and a low circulating erythropoietin level, high WBC in the majority of them but normal platelet counts." (PMID 20126644, 2010). "Furthermore, EPO levels in PV are frequently disproportionately low in relation to the degree of erythrocytosis, in contrast to other causes of polycythemia, where EPO levels are elevated." (PMID 41577837, 2026). "Secondary polycythemia is often caused by conditions that would be expected to generate an increase in serum EPO levels such as smoking, hypoxia, chronic high-altitude exposure, sleep apnea, lung diseases, and EPO-secreting tumors." (PMID 40248540, 2025). "Polycythemia, whether primary (e.g., polycythemia vera) or secondary (e.g., due to chronic hypoxia or EPO-secreting tumors), is often associated with splenomegaly due to increased RBC mass and extramedullary hematopoiesis in the spleen." (PMID 40191193, 2025). "Moreover, the ectopic production of Erythropoietin (EPO) causing erythrocytosis is another PNS that is usually related to hepatic or renal cell cancer." (PMID 38534956, 2024). "Exploring a secondary cause of polycythemia is recommended whenever the EPO level is high." (PMID 39421127, 2024). "Low EPO and prior thrombosis seemed to predict the detection of variants leading to a PV diagnosis, and a positive family history was significantly more common in patients with familial erythrocytosis pathogenic variants." (PMID 39335122, 2024). "Cardiomyopathy could have resulted in polycythemia, but this is usually associated with elevated EPO levels, ruling out primary cardiomyopathy in the differential diagnosis." (PMID 39280364, 2024). "Secondary polycythemia is seldom associated with renal diseases, such as adult polycystic kidney disease, kidney tumors (like renal cell carcinoma and reninoma), renal artery stenosis, and kidney transplant due to increased EPO production." (PMID 36811053, 2023). "Moreover, local renal hypoxia, medications such as testosterone, and pathologic EPO production by malignant disorders can cause secondary polycythemia." (PMID 35805729, 2022). "Hereditary erythrocytosis can be secondary due to, among others, mutations in genes in the oxygen sensing pathway, the erythropoietin (EPO) gene, or genes encoding high-affinity hemoglobins, and are associated with elevated or normal EPO levels." (PMID 35819517, 2022).
polycythemia (continued). "Secondary polycythemia is caused by an elevation of systemic EPO, which is a usual secondary physiologically appropriate response to chronic hypoxia caused by cigarette smoking, hypoxic lung disease, obstructive sleep apnea, cardiopulmonary shunt, and high altitude." (PMID 35805729, 2022). "Conversely, an old case report described a Siamese in a “true polycythemia” secondary to hypoxia, which was associated to tetralogy of Fallot; the resultant decrease in the arterial partial pressure of oxygen stimulated an increased production of erythropoietin, thus causing the polycythemia." (PMID 33802401, 2021). "Hepatotoxicity in HMNDYT1 is thought to be due to cytotoxic manganese overload within hepatocytes; polycythemia is thought to be caused by upregulation of erythropoietin by manganese; and iron anemia through systemic dysregulation of iron homeostasis by excess manganese." (PMID 34315874, 2021). "Interestingly, Irp1–/–-induced elevated Hif2α upregulates EPO, causing the mice to develop polycythemia and pulmonary hypertension." (PMID 34675764, 2021). "Increased red blood cell count may result from primary erythrocytosis (polycythemia vera), but it is often due to secondary causes with increased erythropoietin levels." (PMID 34899081, 2021). "Risk factors for developing erythrocytosis include male gender, retained native kidney, hypertension, renal artery stenosis, a short period of pre‐transplant dialysis, reduced need for pre‐transplant use of EPO or being transfused." (PMID 30426472, 2019). "Systemic repeated EPO treatment may be associated with some side effects such as polycythemia resulting from its erythropoietic activity." (PMID 29385149, 2018). "For instance, erythrocytosis caused by EPO production was found in this case." (PMID 28877745, 2017). "Sung and Lin4 reported that uncontrolled NDI may result in marked hydronephrosis, which may subsequently cause local renal hypoxia, increased erythropoietin production, and polycythemia." (PMID 27258490, 2016). "Several diagnostic algorithms of newly diagnosed (acquired) erythrocytosis investigation are based on erythropoietin levels to differentiate between primary (low erythropoietin levels) with gene alterations and secondary (high erythropoietin levels) erythrocytosis." (PMID 26187587, 2015). "However, the excessive use of EPO can boost the hematocrit, which is detrimental for microcirculatory perfusion in ischemic situations, such as ON, and which causes polycythemia, a condition with abnormally high levels of RBCs." (PMID 24503957, 2014). "The use of serum EPO levels can also be useful in elucidating the cause of erythrocytosis." (PMID 24312736, 2013). "Primary causes of polycythemia are mutations in genes involved in the regulation of erythropoiesis, while secondary polycythemia may develop as a consequence of chronic cardiopulmonary disease or an erythropoietin-secreting process." (PMID 40130200, 2025). "The mechanism underlying polycythemia may be related to increased erythropoietin (EPO) production." (PMID 38524578, 2024). "Hence, androgen-induced erythropoiesis is associated chiefly with average to low EPO levels, while in contrast, secondary polycythemia from chronic hypoxia due to underlying heart disease, lung disease, and obstructive sleep apnea is associated with elevated EPO levels." (PMID 39280364, 2024). "This dose of EPO is higher than the EPO dose, about 150 IU/kg, used to increase hematocrit in chronic renal disease, and a longer duration of treatment of PD subjects with EPO would be expected to cause a prohibitive increase in blood hematocrit leading to polycythemia." (PMID 38035276, 2023). "For systemically secreted proteins such as EPO, precise regulation of gene expression in normal and unhealthy ganglion cells is needed, as dysregulation of EPO expression could cause lethal adverse events, such as polycythemia or thromboembolic events." (PMID 36769310, 2023).
polycythemia (continued). "Furthermore, some rare mutations in the EPO gene itself cause erythrocytosis." (PMID 35750861, 2022). "Notably, treatment with EPO is associated with multiple adverse events, such as hypertension, nausea, headache, thromboembolic events, polycythemia, intracerebral hemorrhage, brain edema, and death, particularly when administered systemically and chronically or at a higher dose." (PMID 36555679, 2022). "Additionally, a unique association between polycythemia and mildly elevated erythropoietin (EPO) levels has been observed in patients, which was linked to inappropriate hypersensitivity of erythroid progenitors to EPO, indicating increased EPOR expression/activity." (PMID 36699028, 2022). "Hypoxia-inducible factors (HIFs) orchestrate response to hypoxia and HIF-2 is the principal regulator of erythropoietin (EPO) production in kidney as underscored by genetic studies in human populations that live at high-altitude and by mutational analysis of patients with familial erythrocytosis." (PMID 33790808, 2021). "Erythrocytosis may be a secondary cause in cases associated with increased RCM or EPO-secretion." (PMID 19946506, 2009). "Myofiber-specific deletion of EPO in the PHD mTKO background abolished polycythemia, demonstrating that this phenotype is driven specifically by muscle-derived EPO." (PMID 41701958, 2026). "On Day 191, the Hb level further increased to 19.0 g/dL, indicating worsening polycythemia, and the serum EPO level increased to 406 mIU/mL." (PMID 40502212, 2025). "Following radiotherapy for the brain metastases, both polycythemia and elevated EPO levels improved rapidly, leading to a diagnosis of erythrocytosis due to EPO production from the metastatic brain tumor." (PMID 40502212, 2025). "Patients with JAK2-positive erythrocytosis had a lower mean EPO than patients with JAK2-negative erythrocytosis (4.4 mU/mL vs. 12.3 mU/mL; p < 0.01)." (PMID 40806795, 2025). "We evaluated the diagnostic accuracy of EPO, JAKPOT, and a combination of low EPO and JAKPOT (EPO-JAKPOT) for predicting JAK2 mutant erythrocytosis." (PMID 40806795, 2025). "In this article, we report a case of SCLC with brain metastases associated with elevated erythropoietin (EPO) levels and polycythemia." (PMID 40502212, 2025). "Testing for monoclonal gammopathies indicative of TEMPI (telangiectasias, erythrocytosis with elevated EPO, monoclonal gammopathy, perinephric fluid collection, and intrapulmonary shunting) syndrome was negative." (PMID 40627222, 2025). "Polycythemia due to erythropoietin secretion and Stauffer syndrome, marked by hepatic dysfunction, are also observed." (PMID 41479787, 2025). "Polycythemia and hyperbilirubinemia are understood to be counterregulatory mechanisms for this state of hypoxia as it triggers erythropoietin secretion and increased red cell production." (PMID 40589878, 2025). "Encapsulation of EPO in a PEGDA hydrogel allows for localized, sustained release, reducing systemic exposure and minimizing the risk of side effects like polycythemia." (PMID 40397370, 2025). "Paraneoplastic polycythemia arises from ectopic erythropoietin (EPO) production, most commonly by renal cell carcinoma or cerebellar hemangioblastomas, leading to elevated red blood cell mass and hyperviscosity." (PMID 40867266, 2025). "Our findings of EPO-induced splenomegaly and immunosuppression in mice share both similarities and differences with the splenic pathology observed in polycythemia patients, particularly those with elevated EPO levels." (PMID 40191193, 2025). "In contrast, our murine model reflects secondary polycythemia induced by exogenous EPO administration, which directly stimulates erythropoiesis and increases RBC mass." (PMID 40191193, 2025). "Hypoxia stimulates erythropoietin (EPO) secretion, resulting in the development of secondary polycythemia.Low temperature promotes enhanced platelet aggregation, thereby increasing blood viscosity." (PMID 40919155, 2025).